CSNK2B (casein kinase 2 beta)
Description:
Regulatory subunit of casein kinase II/CK2. As part of the kinase complex regulates the basal catalytic activity of the alpha subunit a constitutively active serine/threonine-protein kinase that phosphorylates a large number of substrates containing acidic residues C-terminal to the phosphorylated serine or threonine. Participates in Wnt signaling (By similarity). (Microbial infection) Upon infection with Epstein-Barr virus (EBV), the interaction with viral EBNA1 increases the association of CK2 with PML proteins, which increases PML phosphorylation by CK2, triggering the polyubiquitylation and degradation of PML. Seems to also suppress EBV reactivation by mediating ARK2N and JUN at the Z promoter which inhibits BZLF1 transcrition.
Synonyms: CK II beta; CK2N; G5A; Ckb1; Ckb2; CK2B; CSK2B; POBINDS
Tractability: Small molecule: a structure with a bound ligand is known; a high-quality ligand is known. Antibody: its Gene Ontology location is reachable by antibodies, with high confidence. PROTAC: UniProt records ubiquitination sites on it; ubiquitination databases record sites on it; its protein half-life has been measured; a small molecule that binds it is known.
Target class: Kinase; Protein kinase regulatory subunit; Enzyme
Gene: Protein-coding gene on chromosome 6 (31,665,227 to 31,670,343, forward strand). Ensembl gene ENSG00000204435.
Subcellular location: Nucleus
Subcellular location (Human Protein Atlas): Nucleoplasm; Calyx; Mid piece; Nucleoli fibrillar center; Perinuclear theca
Pathways (Reactome):
Circadian clock: Phosphorylation and nuclear translocation of BMAL1 (ARNTL) and CLOCK; Phosphorylation and nuclear translocation of the CRY:PER:kinase complex
Gene expression (Transcription): RUNX1 interacts with co-factors whose precise effect on RUNX1 targets is not known
Immune System: Neutrophil degranulation; SPOP-mediated proteasomal degradation of PD-L1(CD274)
Signal Transduction: Regulation of PTEN stability and activity; WNT mediated activation of DVL
Autophagy: Receptor Mediated Mitophagy
Cell Cycle: Condensation of Prometaphase Chromosomes
Cell-Cell communication: Regulation of CDH1 posttranslational processing and trafficking to plasma membrane
Cellular responses to stimuli: KEAP1-NFE2L2 pathway
Developmental Biology: Signal transduction by L1
Disease: Maturation of hRSV A proteins
Metabolism: Synthesis of PC
Metabolism of proteins: Cooperation of PDCL (PhLP1) and TRiC/CCT in G-protein beta folding
Gene Ontology:
Molecular function: chromatin binding; identical protein binding; protein binding; protein domain specific binding; protein serine/threonine kinase activity; protein-macromolecule adaptor activity; RNA polymerase II-specific DNA-binding transcription factor binding; signaling receptor binding; protein kinase regulator activity
Biological process: adiponectin-activated signaling pathway; endothelial tube morphogenesis; negative regulation of blood vessel endothelial cell migration; negative regulation of proteasomal ubiquitin-dependent protein catabolic process; negative regulation of viral life cycle; positive regulation of activin receptor signaling pathway; positive regulation of SMAD protein signal transduction; symbiont-mediated disruption of host cell PML body; heterochromatin formation; negative regulation of cell population proliferation; positive regulation of DNA-templated transcription; protein-containing complex assembly; signal transduction
Cellular component: chromatin; cytoplasm; extracellular exosome; fibrillar center; nucleoplasm; nucleus; PcG protein complex; plasma membrane; PML body; protein kinase CK2 complex; cytosol; extracellular region; ficolin-1-rich granule lumen; PRC1 complex; secretory granule lumen
Genetic constraint (gnomAD): Loss-of-function variants: 2 observed, 26.58 expected, observed/expected ratio (o/e) 0.0752, 90% interval 0.03 to 0.24. The upper end of that interval is the gene's LOEUF score, 0.24, which puts it in group 1 of 6, group 1 being the genes least tolerant of losing a copy. Missense variants: 103 observed, 274.77 expected, observed/expected ratio (o/e) 0.37, 90% interval 0.32 to 0.44. Synonymous variants: 86 observed, 97.88 expected, observed/expected ratio (o/e) 0.88, 90% interval 0.74 to 1.05.
Gene-disease validity (ClinGen):
ClinGen rates the evidence that CSNK2B causes each of these diseases.
Poirier-Bienvenu neurodevelopmental syndrome (autosomal dominant): Definitive.
Homologues: Orthologues: dog CSNK2B (100% identical), mouse Csnk2b (100% identical), pig CSNK2B (100% identical), rabbit CSNK2B (100% identical), rat Csnk2b (100% identical), tropical clawed frog csnk2b (99% identical), zebrafish csnk2b (99% identical), Drosophila melanogaster CkIIbeta (87% identical), Caenorhabditis elegans kin-10 (73% identical), guinea pig CSNK2B (61% identical).
Diseases named in the same sentence as CSNK2B in open-access papers:
CSNK2B is named in the same sentence as 56 diseases in open-access papers, as found by Europe PMC text mining. Sharing a sentence is not in itself a finding about the gene and the disease. The quoted sentences say what the papers report.
epilepsy (13 papers, 2019 to 2026). A brain disorder characterized by episodes of abnormally increased neuronal discharge resulting in transient episodes of sensory or motor neurological dysfunction, or psychic dysfunction. "The CSNK2B mutation is associated with neurodevelopmental disorders characterized by developmental delays and epilepsy of varying severity." (PMID 41890472, 2026). "In this study, we present four cases of pediatric seizures caused by de novo variants in CSNK2B, with the aim to reinforce the clinical and variant data pertaining to early genetic factors associated with epilepsy." (PMID 40211296, 2025). "Our data suggest that the CSNK2B variant or 6p21.33 deletion should be considered in patients with intellectual disability and epilepsy, especially those characterized by biphasic patterns and digital anomalies." (PMID 39493709, 2024). "The occurrence of a biphasic pattern of epilepsy and pharmacoresistant epilepsy in patients with CSNK2B variants is severely underestimated." (PMID 39493709, 2024). "CSNK2B causes Poirier-Bienvenu neurodevelopmental syndrome, which is characterized by early-onset epilepsy (median 5 months), clustered GTCS, myoclonic seizures, and DD." (PMID 39906551, 2024). "The most frequent manifestations of these subjects with mutations in the CSNK2B gene are epilepsy, developmental delays, and intellectual disabilities." (PMID 35370893, 2022). "Variants in CSNK2B associated with epilepsy and/or intellectual disability (ID)/developmental delay (DD) have been reported in five cases only." (PMID 31784560, 2019). "The reported patients of POBINDS indicate that CSNK2B related epilepsy responds relatively well to VPA." (PMID 40211296, 2025). "This study elucidates the molecular etiology of epilepsy in four cases with POBINDS and expands the mutational spectrum of pathogenic variants in the CSNK2B, highlighting their impact on splicing." (PMID 40211296, 2025). "Drug-resistant epilepsy and a biphasic pattern of epilepsy account for 35% of patients with CSNK2B-related epilepsy." (PMID 39493709, 2024). "Because de novo variants in CSNK2B have been reported to cause intellectual disability and epilepsy, while MTM1 has been linked to X-linked myotubular myopathy, we considered CSNK2B more interesting to investigate its contribution to the disease." (PMID 35571680, 2022). "WES analysis of the trio revealed the presence in the proband of two variants in epilepsy-associated genes, SCN1A (NM_001202435.1) and CSNK2B (NM_001320.5)." (PMID 36360260, 2022). "CSNK2B-related epilepsy had some seizures occurred during febrile disease, but, unlike PCDH19-related epilepsy, the seizures does not have significant fever sensitivity." (PMID 31784560, 2019). "We found nine epileptic patients with pathogenic de novo variants of CSNK2B and summarised the clinical features, effective medication, and genotype-phenotype relation for CSNK2B-related epilepsy." (PMID 31784560, 2019). "Summary of clinical features of patients with CSNK2B related pharmaco-resistant epilepsy." (PMID 39493709, 2024). "Drug-resistant epilepsy accounts for 37% (31/83) of patients with CSNK2B-related epilepsy." (PMID 39493709, 2024). "Summary of clinical features of patients with CSNK2B related biphasic pattern of epilepsy." (PMID 39493709, 2024). "A definite association between phenotype and genotype in CSNK2B gene-related epilepsy has still not been described." (PMID 34983633, 2022). "Phenotypes of CSNK2B clinical and epilepsy characteristics (n = 57)." (PMID 35774559, 2022). "Therefore, we cannot establish a definite correlation between the phenotype and genotype in CSNK2B-related epilepsy at this time." (PMID 31784560, 2019). "In conclusion, our research further demonstrated that pathogenic variants in CSNK2B were associated with epilepsy with or without ID/DD." (PMID 31784560, 2019). "The early onset of CSNK2B-related epilepsy may be related to the high expression at the early stage of infancy." (PMID 31784560, 2019).
epilepsy (continued). "CSNK2B-related epilepsy is relatively easy to be controlled." (PMID 31784560, 2019). "In summary, our research provided evidence that variants in CSNK2B are associated with epilepsy with or without ID/DD." (PMID 31784560, 2019). "So far, the mechanism of CSNK2B variant causing epilepsy is not clear." (PMID 40211296, 2025). "At present, it has been found that the CSNK2B variant leads to significant differences in epilepsy phenotypes in POBINDS cases So far, there have been no reports of CSNK2B related cases dying from seizures, indicating a lower risk of mortality from CSNK2B related epilepsy." (PMID 40211296, 2025). "We suggest that screening of CSNK2B could be included in the most common gene panels for epilepsy." (PMID 34983633, 2022). "Thus, CSNK2B-related epilepsy mostly had an early onset, and GTCS was the most common seizure type." (PMID 31784560, 2019). "CSNK2B is also connected to cell signaling pathways, alongside ITGA6 and Furin, with documented contributions to neurodevelopmental disorders, epilepsy, and the classical GBM subtypes." (PMID 39123468, 2024). "Variants in CSNK2B (OMIM: 115441) were identified in 2 patients through WES (Case 67 and 72), but this gene was not included in our epilepsy gene panel." (PMID 39906551, 2024).
Intellectual disability (11 papers, 2019 to 2024). "Mutations in 6p21.33 have been described to correlate with phenotypes causing mild intellectual disability in human patients, potentially due to the haploinsufficiency of CSNK2B." (PMID 38534351, 2024). "The Poirier-Bienvenu neurodevelopmental syndrome (POBINDS) is a rare disease caused by mutations in the CSNK2B gene, which is characterized by intellectual disability and early-onset epilepsy." (PMID 37020656, 2023). "Recently, a subset of CSNK2B missense variants affecting the Asp32 in the KEN box-like domain were proposed as the cause of a new intellectual disability-craniodigital syndrome (IDCS)." (PMID 36833176, 2023). "CSNK2B deficiency is associated with clinically heterogeneous deficits, including intellectual disabilities, multiple congenital anomalies, development delays, seizures, and short stature." (PMID 35370893, 2022). "We report two new Chinese patients with varying sizes of 6p21.33 deletions encompassing the CSNK2B gene who presented with intellectual disability and seizures." (PMID 39493709, 2024). "In Patient 1, in addition to cranial anomalies and intellectual disability with seizures, digital anomalies were prominent, suggesting that both IDCS and POBINDS belong to a continuous spectrum of CSNK2B-associated phenotypes." (PMID 39493709, 2024). "Conversely, variants in CSNK2B have recently been associated with the Poirier-Bienvenu neurodevelopmental syndrome (MIM: #618732), a neurological disorder characterised by early-onset and possibly refractory seizure, intellectual disability of various degree, and ASD." (PMID 36360260, 2022).
Poirier-Bienvenu neurodevelopmental syndrome (9 papers, 2022 to 2025). "In summary, we presented the clinical phenotypes of four unrelated case with novel heterozygous variants in the CSNK2B gene and expands the spectrum of variants in Poirier Bienvenu neurodevelopmental syndrome." (PMID 40211296, 2025). "CSNK2B deficiency underlies the pathogenesis of Poirier-Bienvenu neurodevelopmental syndrome (POBINDS)." (PMID 40211296, 2025). "Of note, another neurodevelopmental syndrome called Poirier-Bienvenu neurodevelopmental syndrome (POBINDS) exists resulting from mutations in the CSNK2B gene, which encodes for the CK2β protein." (PMID 40677894, 2025). "This syndrome, linked to the CSNK2B gene located on chromosome 6 (6p21.33), now termed the Poirier-Bienvenu Neurodevelopmental Syndrome (POBINDS), has been described in 51 patients." (PMID 35693553, 2022).
breast cancer (8 papers, 2015 to 2025). A primary or metastatic malignant neoplasm involving the breast. "It has also been shown that miR‐4656 regulates the proliferation of breast cancer cell lines by targeting CSNK2B at the transcription level." (PMID 40231553, 2025). "Increasing researches showed the important utility of CSNK2B in diversified carcinomas, e.g., hepatocellular carcinoma, gastric cancer, breast cancer, and colorectal cancer." (PMID 37059591, 2023). "In another study of breast cancer (BC), higher CSNK2B expression was significantly correlated with worse prognosis of patients suffering from BC." (PMID 33928514, 2021). "The HOXC13 and CSNK2B expression increase in breast cancer and play a key role in the progression of breast cancer." (PMID 33073494, 2020). "Through comparison of mRNA levels between adjacent normal tissues and breast cancer tissues, we found that CSNK2B (p = 5.78e-33) and GRPEL1 (p = 4.19e-07) were significantly upregulated in tumor tissues." (PMID 31781497, 2019). "RNA expression levels of CDC2L1, CDC2L2, CCNL1, CCNL2, CSNK2A1, CSNK2A2, and CSNK2B genes in breast cancer subtypes were analyzed." (PMID 25837326, 2015). "Finally, linc00339/miR-4656/CSNK2B signaling pathway was identified and proved to mediate the inhibitory function of Huaier on breast cancer cells." (PMID 31781497, 2019). "Finally, we identified that Huaier could inhibit the proliferation of breast cancer cells through modulating linc00339/miR-4656/CSNK2B signaling pathway." (PMID 31781497, 2019). "High expression of CSNK2B (p = 0.0041, HR = 1.37), GRPEL1 (p = 0.0200, HR = 1.29) and QARS (p = 0.0350, HR = 1.26) were corelated with worse prognosis in breast cancer patients, whereas CCND3, HDAC3, SH3BGRL3, SRM, and UBE2D4 were not correlated with OS." (PMID 31781497, 2019). "Previously, using systems biology approach and cancer signaling networks, we identified top-5 highly expressed and connected proteins (HSP90AB1, CSNK2B, TK1, YWHAB and VIM) in the invasive MDA-MB-231 breast cancer cell line." (PMID 27527857, 2016).
hepatocellular carcinoma (7 papers, 2020 to 2023). A malignant tumor that arises from hepatocytes. "Studies have shown that TNFAIP1 mediates DNA replication, repair, and cell cycle regulation by interacting with PCNA, and it regulates hepatocellular carcinoma progression by interacting with CSNK2B." (PMID 37886961, 2023). "Overexpression of CSNK2B in hepatocellular carcinoma and colorectal cancer increases cell division and prevents death." (PMID 36544483, 2022). "In a recent study, Xiao and co-workers found that CSNK2B attenuates the inhibition of NF-κB in hepatocellular carcinoma." (PMID 34227026, 2021). "For example, overexpression of CSNK2B has been found to activate the NF-κB signaling in hepatocellular carcinoma (HCC), thus promoting cell proliferation and inhibiting cell apoptosis of HCC." (PMID 33928514, 2021).
schizophrenia (7 papers, 2018 to 2025). A major psychotic disorder characterized by abnormalities in the perception or expression of reality. "Sherlock integrative analysis shows that ALMS1, GLT8D1, and CSNK2B are schizophrenia risk genes, which are validated using independent brain expression quantitative trait loci (eQTL) data and integrative analysis method (SMR)." (PMID 29483533, 2018). "Finally, we identified CSNK2B, TOMM40, MAP1LC3B, MFN1, CSNK2A2, PGAM5 and ATG12 as the diagnostic genes for schizophrenia." (PMID 39355378, 2024). "Furthermore, the most significant proteins for suicide in the WGCNA analysis included CAPNS1 (Calpain Small Subunit 1), which is suggested to play a neuroprotective role, and CSNK2B and PTP4A2, implicated as biomarkers for psychiatric disorders such as major depressive disorder and schizophrenia." (PMID 35383147, 2022). "These convergent lines of evidence suggest that the ALMS1, CSNK2B, and GLT8D1 genes may be involved in pathophysiology of schizophrenia." (PMID 29483533, 2018).
gastric cancer (4 papers, 2021 to 2023). A primary or metastatic malignant neoplasm involving the stomach. "A study highlight, that NELFE-Wnt/β-catenin-CSNK2B hubs can be new candidate targets in gastric cancer through their positive connection, as they found that all these hubs are upregulated." (PMID 37047552, 2023). "In vitro and in vivo experiments on gastric cancer (GC) concluded that CSNK2B promotes the proliferation and migration of GC cells." (PMID 37312186, 2023).
autism (3 papers, 2023 to 2026). Persistent deficits in social interaction and communication and interaction as well as a markedly restricted repertoire of activity and interest as well as repetitive patterns of behavior.
Intellectual Disability-Craniodigital Syndrome (3 papers, 2022 to 2024). "To date, 16 patients have been reported in the literature with POBINDS and 2 patients have been reported with craniodigital intellectual disability syndrome related to mutations in the CSNK2B gene." (PMID 34983633, 2022).
COVID-19 (2 papers, 2023). A disease caused by infection with severe acute respiratory syndrome coronavirus 2. "In the validation dataset, we found consistent metabolic trends in T cells; namely, we found that COVID-19 T cells downregulate key mitophagy genes FUNDC1, PINK1, and CSNK2B and upregulate key Rho GTPase genes RHOA, RHOBTB1, and ARAP3 as well as MTOR compared to HIV-1+ individuals." (PMID 36992700, 2023).
Seizure (2 papers, 2024 to 2025). A seizure is an intermittent abnormality of nervous system physiology characterized by a transient occurrence of signs and/or symptoms due to abnormal excessive or synchronous neuronal activity in the brain. "Seizures have been identified in most patients with CSNK2B-related Poirer-Bienvenu Neurodevelopment syndrome (POBINDS)." (PMID 39493709, 2024).
asthma (1 paper, 2019).